CYP27A1 (cytochrome P450 family 27 subfamily A member 1)
Diseases named in the same sentence as CYP27A1 in open-access papers (continued):
Sharing a sentence is not in itself a finding about the gene and the disease.
cholelithiasis (1 paper, 2025). The presence of crystallized deposits forming in the gallbladder or biliary tree, primarily composed of cholesterol, bilirubin, and bile. "PPARα suppresses the activity of cholesterol 7α-hydroxylase (CYP7A1) and sterol 27-hydroxylase (CYP27A1), the rate-limiting enzymes in bile acid synthesis, leading to a decrease in bile acid production and the likely development of biliary tract–related adverse effects, including cholelithiasis." (PMID 41368577, 2025).
chronic obstructive pulmonary disease (1 paper, 2018). A chronic and progressive lung disorder characterized by the loss of elasticity of the bronchial tree and the air sacs, destruction of the air sacs wall, thickening of the bronchial wall, and mucous accumulation in the bronchial tree. "Additionally, protein expression of CYP27A1 is higher in lung tissues from chronic obstructive pulmonary disease patients than normal lung tissues." (PMID 30190703, 2018).
dyslipidaemia (1 paper, 2019). "Thus, altered pancreatic levels of Cyp27A1, ADXR, TSPO and LXRα are triggered in response to genetic obesity in rodents, a condition characterised by dyslipidaemia and hyperinsulinaemia." (PMID 30819824, 2019).
endometriosis (1 paper, 2025). The growth of functional endometrial tissue in anatomic sites outside the uterine body. "Overall, HMGCR and CYP27A1 seem to be promising biomarkers for the identification of endometriosis and the assessment of its severity, respectively." (PMID 40527850, 2025). "In conclusion, HMGCR and CYP27A1 were identified as potential markers for endometriosis and its severity, respectively." (PMID 40527850, 2025). "Additionally, 11 core genes have been pinpointed, with HMGCR and CYP27A1 validated as potential biomarkers for the identification and severity assessment of endometriosis, respectively." (PMID 40527850, 2025). "Additionally, 11 core genes were identified, with HMGCR and CYP27A1 validated as potential markers for diagnosing endometriosis and assessing its severity, respectively." (PMID 40527850, 2025).
fibrosis (1 paper, 2022). the formation of excess fibrous connective tissue in an organ or tissue in a reparative or reactive process. "The mRNA levels of Cyp8b1 and cytochrome P450, family 27, subfamily a, polypeptide 1 (Cyp27a1) were significantly decreased in the fibrosis groups." (PMID 35637968, 2022).
frontotemporal dementia (1 paper, 2012). Frontotemporal dementia (FTD) comprises a group of neurodegenerative disorders, characterized by progressive changes in behavior, executive dysfunction and language impairment, as a result of degeneration of the medial prefrontal and frontoinsular cortices. "Two heterozygous mutations in CYP27A1 have been reported in a patient with atypical CTX and frontotemporal dementia characteristics." (PMID 22509407, 2012).
Genetic obesity (1 paper, 2019). "It is possible that induction of Cyp27A1 may therefore be an autocrine or paracrine response to limit adipocyte hyperplasia during overfeeding, and could exert a similarly protective function in pancreatic tissue to prevent cholesterol accumulation in genetic obesity." (PMID 30819824, 2019).
glaucoma (1 paper, 2024). Increased pressure in the eyeball due to obstruction of the outflow of aqueous humor. "Here, we also used variants in the CYP2R1, CYP27A1 and CYP27B1 genes for evidence of association with glaucoma." (PMID 39202443, 2024).
head and neck cancer (1 paper, 2023). A primary or metastatic malignant neoplasm affecting the head and neck. "Another study examined the influence of genetic sequence variants (GSVs) in the vitamin D3 metabolism pathway, candidate-based GSVs, i.e., VDR, GC, CYP24A1, CYP27A1, CYP27B1, and CYP2R1, on overall survival (OS) and second primary cancer (SPC) in head and neck cancer patients." (PMID 37299554, 2023).
hepatoblastoma (1 paper, 2024). Hepatoblastoma (HB) is a malignant hepatic tumor and is the most common pediatric liver cancer. "In addition, GH and IGF1 appear to increase the activity of CYP27A1, a multifunctional cytochrome P450 enzyme which, among its complex functions, catalyses the 25 hydroxylation of vitamin D in hepatoblastoma cells." (PMID 39149044, 2024).
insulinoma (1 paper, 2019). "These putative relationships were explored further in rodent BRIN-BD11 insulinoma cells; while human pancreatic islets and β-cells are known to express CYP27A1, rodent insulinoma cells do not, indicating that this protein is not an essential requirement for glucose-stimulated insulin secretion." (PMID 30819824, 2019).
Klinefelter syndrome (1 paper, 2025). A sex chromosome disorder caused by the presence of an extra X chromosome in the male karyotype. "Trio-based exome sequencing identified a homozygous pathogenic variant in CYP27A1 consistent with CTX, while conventional G-banded karyotyping revealed a 47,XXY chromosomal pattern, confirming Klinefelter syndrome." (PMID 41226549, 2025).
Krabbe disease (1 paper, 2022). A lysosomal disorder that affects the white matter of the central and peripheral nervous systems.
leprosy (1 paper, 2024). Leprosy is a chronic infectious disease affecting primarily the skin and peripheral nervous system. "In the E-MTAB-10318 dataset, APOE, CYP27A1, FADS1, and SOAT1 showed higher expression levels in leprosy compared to the control group." (PMID 38273053, 2024). "In leprosy, the expression levels of APOE and CYP27A1 were positively correlated with the levels of 18 immune cell types." (PMID 38273053, 2024).
liver cancer (1 paper, 2020). An epithelial or non-epithelial malignant neoplasm that arises from the liver. "At the cellular level, YBX3 and CH25H were highly expressed in liver cancer cell lines, and ABCA6, PLIN5, AMACR, AKR1D1, CYP27A1, CYP46A1 were highly expressed in liver cancer cell lines in CCLE." (PMID 32627826, 2020).
liver cirrhosis (1 paper, 2016). "Reduction in 25(OH)D3 levels is possibly due to downregulation of the synthetic hydroxylase CYP27A1 and concurrent upregulation of degrading CYP24A1 in patients with liver cirrhosis." (PMID 27399065, 2016).
nonalcoholic fatty liver disease (1 paper, 2018). "The methylation of CYP27A1 has been reported to be associated with the balance of bile acid in nonalcoholic fatty liver disease and in drug metabolism." (PMID 30208925, 2018).
oral cancer (1 paper, 2020). "This study provides novelty by showing that mRNA levels of MAOB, NAB2, COL3A1, NPIPB4, CYP27A1, and SIAE were significantly reduced in the saliva of oral cancer patients." (PMID 31963366, 2020).
Pleural effusion (1 paper, 2015). The presence of an excessive amount of fluid in the pleural cavity. "For example, we could identify strong expression of CYP27A1 in two newly established ERα metastatic cell line models derived from pleural effusion of AI-resistant patients." (PMID 26610607, 2015).
pregnancy diseases (1 paper, 2017). "Based on our results, a relevant involvement of impaired CYP27A1 expression in pregnancy diseases associated with placental and hepatic dysfunction can be ruled out." (PMID 28376740, 2017).
primary biliary cholangitis (1 paper, 2018). Primary biliary cholangitis (PBC) is a chronic and slowly progressive cholestatic liver disease of autoimmune etiology characterized by injury of the intrahepatic bile ducts that may eventually lead to liver failure. "However, activity of CYP27A1 increases significantly in cholestatic disorders such as primary biliary cholangitis (PBC) and might contribute to generation of CDCA." (PMID 30150987, 2018).
Primary immunodeficiency (1 paper, 2024). "For instance, CTSD is involved in the pathways of ‘Notch signaling pathway,’ CEBPD and CYP27A1 simultaneously mediate ‘T cell receptor signaling pathway,’ ‘Primary immunodeficiency’ and ‘bacterial infection’ signal pathways." (PMID 38451044, 2024).
progressive familial intrahepatic cholestasis type 3 (1 paper, 2020). Progressive familial intrahepatic cholestasis type 3 (PFIC3), a type of progressive familial intrahepatic cholestasis (PFIC), is a late-onset hereditary disorder in bile formation that is hepatocellular in origin. "Overall, in this group, one patient was diagnosed with progressive familial intrahepatic cholestasis type 3 (PFIC-3), one patient was diagnosed with bile acid synthesis defect (CYP27A1 deficiency), and one patient was diagnosed with mitochondrial depletion syndrome (DGUOK deficiency)." (PMID 32793533, 2020).
prostate tumors (1 paper, 2018). "Analysis of these genes in patient samples from the TGCA dataset using the MethHC database (methhc.mbc.nctu.edu.tw) confirmed significant hypermethylation of the DKK3, PTGS2, SLC16A5, HFE, and CYP27A1 promoters in prostate tumors, compared to normal prostate." (PMID 29843383, 2018).
renal carcinoma (1 paper, 2025). A carcinoma arising from the epithelium of the renal parenchyma or the renal pelvis. "Previous studies confirmed that CYP27A1 catalyzes the production of 27-hydroxycholesterol (27-HC) from cholesterol and exhibits a significant growth inhibitory effect in renal cancer cells." (PMID 40755754, 2025).
Retinal dysplasia (1 paper, 2025). Abnormal growth and differentiation, structure and appearance of the retina present from birth. "The overview of the entire region demonstrates the position of BICF2G630130992 in the CYP27A1 gene which was identified as a tentative association with retinal dysplasia in the population of 36 samples of the Czechoslovakian Wolfdog." (PMID 40005930, 2025). "The results of our genome-wide case–control association study revealed one SNP on CFA37 (BICF2G630130992, p = 1.29 × 10−6) localised within the first intron of the CYP27A1 gene that was significantly associated with retinal dysplasia in Czechoslovakian Wolfdog." (PMID 40005930, 2025). "The localization of the SNP marker BICF2G630130992 in the intron of the CYP27A1 gene allowed us to consider this gene as a potential candidate gene for retinal dysplasia in the breed." (PMID 40005930, 2025).
seminoma (1 paper, 2023). A radiosensitive malignant germ cell tumor found in the testis (especially undescended), and extragonadal sites (anterior mediastinum and pineal gland). "Using TCGA mRNA expression of anabolic (CYP2R1, CYP27A1 and CYP27B1) and catabolic (CYP24A1) Vitamin D enzymes, positive (PTHLH, IFNG, and TNF) and negative (FGF23) feedback regulators could also clearly distinguish between pure seminomas and NSGCT." (PMID 37242266, 2023).
vitiligo (1 paper, 2026). Generalized well circumscribed patches of leukoderma that are generally distributed over symmetric body locations and is due to autoimmune destruction of melanocytes. "Consistently, immunohistochemical analysis revealed diminished CYP27A1 expression in melanocytes within vitiligo lesions." (PMID 42272107, 2026).
tumor (67 papers, 2010 to 2026). "CYP7B1, the key enzyme responsible for the catabolism of 27‐HC, is associated with increased recurrence‐free survival, whereas the expression of the 27‐HC synthesising enzyme CYP27A1 is linked to unfavourable tumour characteristics." (PMID 37614064, 2023). "High CYP27A1 expression of both protein and mRNA were associated with adverse tumor pathological characteristics such as NHG III (P= 0.002 and P < 0.001, respectively), and high Ki67 expression (P < 0.001 for both)." (PMID 34556659, 2021). "The expression of cytochrome P450 CYP27A1, which converts cholesterol to 27-hydroxy cholesterol, is high in epithelial breast tumors, and its expression is positively associated with the tumor grade." (PMID 33467111, 2021). "Intratumoral CYP27A1 expression was associated with unfavorable tumor characteristics and significantly impaired survival with differential effects observed between the time periods 0–5 years and greater than 5 years after diagnosis based on menopausal status." (PMID 33176848, 2020). "Tumor CYP27A1 protein expression was associated with lower circulating HDL concentrations, while tumor CYP7B1 was associated with lower triglycerides." (PMID 32075687, 2020). "Multiple human ER+ breast cancer cell lines, breast tumour samples and tumour-associated macrophages have elevated expression of Cyp27a1." (PMID 32998240, 2020). "CYP27A1 expression and 27-hydroxycholesterol promote tumor growth and are associated with reduced progression-free survival in breast and ovarian cancer." (PMID 32727400, 2020). "In aggressive tumor tissues, high CYP27A1 expression was found in both tumor cells and tumor-associated macrophages (TAMs)." (PMID 30283400, 2018). "Notably, in tumour models, Cyp27a1 deficiency led to increased tumour growth, whereas LXR activation elicited anti-tumour responses dependent on adaptive immunity." (PMID 39567700, 2025). "In addition, the expression of CYP27A1 was lower in HCC tumor than adjacent normal tissue, and lower expression of CYP27A1 in tumor tissue was associated with worse OS in TCGA and GSE14520 cohorts." (PMID 36872411, 2023). "In addition, high cholesterol diet-induced macrophage infiltration (CD68 positive cells) in tumor microenvironment, which was reduced by Cyp27A1 deficiency." (PMID 35379924, 2022). "Conversely, the low tumour expression of CYP27A1 was associated with the lower expression of ER-β." (PMID 35011656, 2021). "The strong positive associations between CYP27A1 expression with aggressive tumor characteristics like NHG III and high Ki67 and the finding that high CYP27A1 is associated with favorable prognosis are perplexing and prompted us to explore the joint impact of these markers on prognosis." (PMID 34556659, 2021). "For example, higher levels of CYP27A1 protein is associated with higher tumor grade." (PMID 32650428, 2020). "CYP27A1 gene and protein expression were decreased in primary tumor samples, as compared with these in the normal samples." (PMID 37817081, 2023). "On the other hand, cholesterol can be hydroxylated by CYP27A1 at the ultimate methyl carbon of its side chain to give 27-hydroxycholesterol ((25R)-Cholest-5-ene-3beta,26-diol, 27HC), which is a tumor promoter for ER(+) BC." (PMID 37981011, 2023). "Experimental research investigating the involvement and regulatory roles of CYP27A1 in the phenotypes of HNSC tumor cells is warranted." (PMID 37210507, 2023). "We also found that TUBB2B modulates cholesterol metabolism via targeting CYP27A1, an enzyme responsible for the conversion of cholesterol to 27-hydroxycholesterol, to promote tumor progression." (PMID 36872411, 2023). "27-hydroxycholesterol (27HC) is produced by CYP27A1 and is a tumor promoter in estrogen receptor alpha-positive BC (ER(+) BC)." (PMID 37981011, 2023).
tumor (continued). "The main findings of the current research identified 3 immune-related genes (PLA2G2D, TNFAIP8L2, and CYP27A1) which are likely to play highly significant roles in lipid metabolism-mediated tumor immunity regulation in HNSC." (PMID 37210507, 2023). "The expressions of each of the variables, namely, G9a nuclear, G9a cytoplasmic, G9a total, CYP7B1 and CYP27A1, were also analysed with regard to tumour grade and menopausal status using the median test." (PMID 37614064, 2023). "The transcription level of CYP27A1 is positively correlated with disease-free survival and negatively correlated with tumor grade." (PMID 35075375, 2022). "High cholesterol diet mainly promoted colonization of tumor cells in lung tissue, which was restrained by Cyp27A1 knockdown and strengthened by Cyp7B1 knockdown, consistent with Hematoxylin and Eosin (HE) staining." (PMID 35379924, 2022). "Data from the publicly available METABRIC and TCGA gene expression databases indicated that tumours with high levels of CYP27A1 (and thus expected elevated 27OHC) also presented an increased expression of IGF-I." (PMID 35011656, 2021). "An interrogation of some publicly available datasets reveals that the enzymes Ch25h and Cyp27a1 are expressed in a range of cells within tumours." (PMID 32998240, 2020). "Cholesterol can also be converted to 27-hydroxycholesterol by cytochrome P450 oxidase CYP27A1, which is expressed by both tumor cells and TAMs." (PMID 32727400, 2020). "In premenopausal women, tumor CYP27A1 protein expression was associated with higher circulating DHEAS concentrations, and in perimenopausal women, tumor CYP7B1 was associated with lower testosterone." (PMID 32075687, 2020). "When the production of CYP27A1 is cut off, it can significantly reduce the distant metastasis of tumor cell-related models." (PMID 33096860, 2020). "In this study, tumor-specific CYP27A1 expression was used as a surrogate for intratumoral 27HC levels to investigate the impact on tumor biology and outcome in clinical BC." (PMID 33176848, 2020). "Compared with normal tissues, the expression of 27HC in malignant breast tissues is significantly higher, and the increase of synthase CYP27A1 can improve the tumor grade." (PMID 33096860, 2020). "CYP27A1 demonstrated great potentials as a biomarker of aggressive tumor biology and late lethal disease in postmenopausal patients with ER+ BC." (PMID 33176848, 2020). "It appears that the enzymes ChEH, HSD11B1 and HSD11B2 and CYP27A1 sit at a fulcrum balancing the formation from 5α,6-EC of the tumour suppressor DDA and from 5,6-EC, through 3β,5α,6β-triol, the oncometabolite 3β,5α-diHC-6O or the bile acid 3β,5α,6β-triHBA." (PMID 31009661, 2019). "A recent study showed that metabolic formation of 27-OHC by CYP27A1 increased BC tumor growth and metastasis in mice by acting as agonist of both ER and Liver X receptor (LXR) nuclear receptors, and that it correlates with tumor grade in human specimens." (PMID 31027259, 2019). "When the anatomical site of the tumour was stratified as proximal colon, distal colon or rectum, significant associations were found with expression of CYP8B1, CYP27A1 and CYP51A1." (PMID 27341022, 2016). "Patients with strongly scoring tumours for CYP27A1 (n=16) had decreased survival, with a mean survival of 59 months (95% CI 35-84) in this group." (PMID 27341022, 2016). "However, recent studies on tumor infiltrating myeloid cells led to opposite understanding regarding the role of CYP27A1 in carcinogenesis." (PMID 40630116, 2025). "Therefore, we performed tumor-infiltrating immune cells analysis to gain a deeper understanding of the role played by CYP27A1 in LUAD." (PMID 37817081, 2023). "Besides, the low CYP27A1 expression was also related to worse prognosis in the N0 subgroup of N stage (p = 0.03), left subgroup of anatomic neoplasm subdivision (P = 0.001), and male subgroup of gender (p = 0.021)." (PMID 37817081, 2023).